MGMT (O-6-methylguanine-DNA methyltransferase)
Diseases named in the same sentence as MGMT in open-access papers (continued):
Sharing a sentence is not in itself a finding about the gene and the disease.
pancreatic cancer (11 papers, 2009 to 2025). "We leveraged sequencing data from The Cancer Genome Atlas (TCGA), the Clinical Proteomic Tumor Analysis Consortium 3 (CPTAC‐3), and the (Australian Pancreatic Cancer Genome Initiative) PACA‐AU cohorts to characterize MGMT‐silenced PAC." (PMID 39618336, 2024). "To investigate the role of MGMT in PanNET progression, we examined the expression level of MGMT in various human and mouse pancreatic cancer cell lines (SPNE1, NIT‐1, QGP‐1, Beta‐TC6, MIN6, and Bon‐1)." (PMID 39041891, 2024). "Of note, MGMT was found methylated more frequently in samples with rare pancreatic cancer histology as compared to usual ductal adenocarcinomas." (PMID 39618336, 2024). "They found that haplotypes of O6-methylguanine-DNA methyltransferase (MGMT), MSH6, PMS1 Homolog 2 (PMS2), PMS2-like 3 (PMS2L3), and tumour protein 73 (TP73) were significantly associated with an increased pancreatic cancer risk (P = 0.0015)." (PMID 29069866, 2017). "Of course, the small group of 13 analysed patients does not allow us to support the exact role of hypermethylation of RASSF 1A and/or MGMT on pancreatic cancer, yet." (PMID 22276000, 2009). "The results show that there was loss expression of MGMT, ERCC1, hMSH2, and hMLH1 in the course of genesis of pancreatic cancer induced by DMBA in rats, which might be the mechanism of carcinogenesis by DMBA." (PMID 24502441, 2014). "The DNA-repair proteins, including MGMT, ERCC1, hMSH2, and hMLH1, might play an important role in the genesis of pancreatic cancer induced by DMBA in rats." (PMID 24502441, 2014). "Therefore, testing the expression of MGMT, ERCC1, hMSH2, and hMLH1 in pancreatic cancer might play an important role in guiding the treatment of human pancreatic cancer." (PMID 24502441, 2014). "The expression levels of MGMT, ERCC1, hMSH2, and hMLH1 in pancreatic cancer and non-cancerous pancreatic tissues was detected and their effect on the process of inducing cancer by DMBA was assessed." (PMID 24502441, 2014).
astrocytic tumor (10 papers, 2007 to 2024). A glial tumor of the brain or spinal cord showing astrocytic differentiation. "Immunohistochemically, the astrocytic tumor cells showed weakly positive on the methylation of genes of O-6-methylguanine DNA methyltransferase (MGMT) promoter and strong mutation of phosphatase and tensin homolog (PTEN) genes." (PMID 25889578, 2015). "While methylation of the MGMT promoter had a clear prognostic significance in the entire cohort of malignant astrocytic tumors, isolated analysis of patients diagnosed with GBM revealed only a trend in this direction." (PMID 31623667, 2019). "Our results demonstrated that all three cases with progression to astrocytic tumors had an unmethylated MGMT promoter in primary tumors but subsequent MGMT methylation; MGMT methylation was correlated with isolated 1p deletion but not 19q deletion." (PMID 23826216, 2013). "Therefore, the only verified prognostic markers for astrocytic tumors remain the IDH1/2 mutation, 1p/19q translocation, and the presence of an MGMT mutation." (PMID 28845375, 2017). "We observed that ATRX-low astrocytic tumors harbored lower MGMT expression." (PMID 25971279, 2015). "Interestingly, we observed that astrocytic tumors with lower ATRX expression companied with MGMT (O6-methylguanine–DNA methyltransferase) hypermethylation and downregulation." (PMID 25971279, 2015). "In addition, one locus, MGMT, showed a stochastic accumulation in methylation starting around age 50, with potential implications for the tumor biology of astrogliomas." (PMID 17878930, 2007). "Pooling all malignant astrocytic tumors with available IDH and MGMT status three molecular groups allowed further analysis regarding OS: IDH-mutated and MGMT methylated, IDH-wildtype and MGMT methylated and IDH-wildtype and MGMT not methylated." (PMID 31623667, 2019). "Unlike other, much more established markers in astrocytic tumors, such as the presence of an IDH1/2 mutations, 1p/19q translocation and MGMT mutations, Ki-67 does not seem to be of viable significance in the everyday pathological verification of these oncological entries." (PMID 28845375, 2017). "Furthermore, a limitation of our search method is we did not differentiate the significance of MGMT methylation between IDH-mutant and IDH-wildtype astrocytic tumors." (PMID 38521933, 2024).
pituitary adenomas (10 papers, 2014 to 2025). "Initial reports from pituitary adenomas confirmed this association of a low MGMT immunoexpression with a positive response to TMZ treatment." (PMID 28900805, 2017). "MGMT promoter methylation has also been associated with tumor regrowth in pituitary adenoma." (PMID 31139150, 2019). "However, few systematic studies are available that examine the association between MGMT promoter methylation and MGMT expression in pituitary adenomas." (PMID 26400193, 2015). "Studies have suggested O6-methylguanine-DNA methyltransferase (MGMT) as the key factor responsible for chemoresistance of aggressive pituitary adenomas to the currently most promising chemotherapeutic drugs temozolomide (TMZ) and 2-methoxyestradiol (2ME)." (PMID 31244652, 2019). "The aim of this study was to validate the current IHC method for assessment of MGMT protein expression in pituitary adenomas." (PMID 29344904, 2018). "Despite the established role of O6-methyl-guanine-DNA methyltransferase (MGMT) as a marker for temozolomide response, consensus of the most reliable method to assess MGMT expression in pituitary adenomas is still missing." (PMID 29344904, 2018). "In conclusion, our data confirm that the current method using formaldehyde tissue fixation and IHC reveals stable and reliable results of MGMT assessment in pituitary adenomas." (PMID 29344904, 2018). "Overall eight pituitary adenoma samples fixated at six different time points, 46/48 (96%) formaldehyde cases remained positive (MGMT expression > 50%), while 39/48 (81%) cases showed stable results in the RCL2 group (p = 0.025)." (PMID 29344904, 2018). "First, we compared the stability of MGMT protein expression after pituitary adenoma removal in formaldehyde vs. RCL2 in a time dependent mode." (PMID 29344904, 2018). "Despite the established role of MGMT as a possible marker for TMZ response, consensus of the most reliable method to assess MGMT expression in pituitary adenomas is still missing." (PMID 29344904, 2018). "The tissue samples of 8 macroadenomas with positive IHC MGMT expression (> 50%) were investigated: first, we compared the time dependent stability of MGMT protein expression after pituitary adenoma removal between formaldehyde vs. RCL2." (PMID 29344904, 2018). "Our data confirm that the current method using formaldehyde tissue fixation and IHC reveals stable and reliable results of MGMT assessment in pituitary adenomas." (PMID 29344904, 2018). "To date, MGMT immunoexpression has been assessed in pituitary adenomas for prediction of the response to TMZ treatment." (PMID 28900805, 2017). "There are seven cohort studies that referred to the relationship of MGMT expression with tumor recurrence or invasiveness pituitary adenoma." (PMID 28152515, 2017). "More cases are needed to create a more accurate profile of MGMT expression in each subtype of pituitary adenoma." (PMID 26400193, 2015). "The data showed that in 197 different histological subtypes of pituitary adenomas (PAs), 64.9% of them were D2R high expression, 86.3% were MGMT low expression and 58.9% were VEGF high expression." (PMID 25027022, 2014). "MGMT expression is often low in aggressive pituitary adenomas (PAs) and recurrent PAs." (PMID 28152515, 2017). "In the future, MGMT status may therefore be considered to be an additional marker for understanding the biological behavior of pituitary adenomas." (PMID 28900805, 2017). "MGMT (O6-methyl-guanine-DNA methyltransferase) and MSH6 (mutS homolog 6) immunoexpression have been linked to the response to TMZ treatment and MGMT immunoexpression has been additionally linked to early recurrence of non-functioning pituitary adenomas." (PMID 28900805, 2017).
pituitary adenomas (continued). "However, in another study, only 50 % of Crooke’s cell adenomas (n = 12) showed low-level MGMT staining, although all subtype I pituitary adenomas (n = 7) were immunopositive at <10 %." (PMID 26400193, 2015). "Therefore, the role of promoter methylation in regulating MGMT expression in pituitary adenomas remains controversial." (PMID 26400193, 2015). "However, systematic studies have identified a role for MGMT promoter methylation in silencing among pituitary adenomas." (PMID 26400193, 2015). "Moreover, although the majority of sporadic pituitary adenomas are monoclonal, MGMT staining was vastly different between tumors, which again suggested that transcriptional modifications are involved in regulating MGMT expression." (PMID 26400193, 2015). "The MGMT status in pituitary adenomas has been evaluated in several previous studies by immunostaining, showing variable expression levels in different subtypes of pituitary adenomas." (PMID 26400193, 2015). "Therefore, in the future, MGMT status may be considered an additional marker for understanding the biological behavior of pituitary adenomas." (PMID 28900805, 2017). "The aim of this study was to assess the prognostic value of MGMT and MSH6 immunoexpression for aggressive functioning pituitary adenomas." (PMID 28900805, 2017). "Immunohistochemistry and western blot were performed to detect the expression of expression of D2R, MGMT and VEGF in pituitary adenoma tissue samples." (PMID 25027022, 2014). "From our observation that low-to-moderate MGMT immunoexpression correlates with early recurrence in non-functioning pituitary adenomas, the aim of the current study was to investigate the status of MGMT and MSH6 immunoexpression in a consecutive series of recurrent functioning macroadenomas." (PMID 28900805, 2017). "Notably, recent data implies that promoter methylation is not the leading mechanism contributing to low pituitary adenoma MGMT expression." (PMID 26400193, 2015).
anaplastic gliomas (9 papers, 2011 to 2024). "Another phase II clinical trial combined TMZ with an O6-methylguanine-DNA methyltransferase (MGMT inhibitor) O6-benzylguanine (O6-BG) to rebuild drug sensitivity in TMZ-resistant anaplastic glioma." (PMID 31938069, 2020). "Recently, IDH1 mutation was found to determine the prognostic and predictive value of MGMT promoter methylation in anaplastic gliomas." (PMID 25977882, 2015). "Recent studies in anaplastic glioma suggest a prognostic value for MGMT methylation." (PMID 22810491, 2012). "Hence, the association of methylated MGMT with CIMP was much stronger in low grade and anaplastic glioma than in the TCGA-GBM." (PMID 22810491, 2012). "In contrast, other studies in anaplastic gliomas have shown that MGMT-methylation status dose not only influence outcome after alkylkating chemotherapies but also radiotherapy and may therefore be prognostic rather than predictive." (PMID 21910919, 2011). "This association of CIMP with MGMT methylation may provide the key to understand why MGMT methylation is associated with a prognostic and not a predictive value for benefit from alkylating agent containing chemotherapy in anaplastic glioma as suggested by two independent clinical trials." (PMID 22810491, 2012). "Further, recent studies indicate that MGMT promoter methylation has strong prognostic relevance even in anaplastic gliomas but irrespective of sensitivity of alkiling agents." (PMID 22264301, 2012). "Other studies in anaplastic gliomas have shown that MGMT promoter methylation status did not only influence patient outcome after chemotherapy but also impacted outcome after radiotherapy and may therefore be prognostic rather than predictive." (PMID 34257620, 2021).
hepatocellular carcinoma (9 papers, 2003 to 2025). A malignant tumor that arises from hepatocytes. "Hepatocellular carcinoma patients with decreased MGMT were observed to have a poor prognosis and advanced disease stage." (PMID 33976347, 2021). "Patients with advanced hepatocellular carcinoma have been treated with temozolomide plus a MAPK/ERK inhibitor (U0126) because this combination increases the susceptibility of HCC cells to TMZ and down-regulates MGMT expression by blocking the MAPK/ERK signaling pathway." (PMID 38817857, 2024). "However, radiation exposure may increase MGMT levels in cancer cells, as demonstrated for rat hepatoma." (PMID 34639014, 2021).
metastatic melanoma (9 papers, 2003 to 2021). A melanoma that has spread from its primary site to another anatomic site. "We also investigated polymorphisms of the MGMT gene in patients with metastatic melanoma in order to explore the possible role of these polymorphisms in DTIC-based chemotherapy." (PMID 14562026, 2003). "Thus, MGMT expression appears to be more related to response to chemotherapy than MGMT polymorphisms in patients with metastatic melanoma." (PMID 14562026, 2003). "Further studies supported that MGMT was also a predictor for clinical response to the DTIC-based therapy in patients with metastatic melanoma." (PMID 33816296, 2021). "Biopsy samples from 122 patients with metastatic melanoma being treated with TMZ in two multicenter studies of the Dermatologic Cooperative Oncology Group were investigated for MGMT promoter methylation." (PMID 20736948, 2010). "In a subset of six patients with accessible metastatic melanoma deposits, MGMT activity was assessed in PBMCs and tumour at baseline and 4 h after the initiation of treatment." (PMID 20628383, 2010). "The correlation of MGMT expression levels with clinical response to chemotherapy was investigated in 79 patients with metastatic melanoma." (PMID 14562026, 2003). "We first assessed MGMT mRNA and protein levels and used them as a biomarker for intrinsic TMZ resistance in our panel of 12 human metastatic melanoma cell lines." (PMID 32899791, 2020). "Our data indicate that MGMT expression had a significant correlation to clinical response, suggesting that MGMT may be an important drug resistance factor against DTIC-based chemotherapy in patients with metastatic melanoma." (PMID 14562026, 2003).
diffuse large B-cell lymphoma (8 papers, 2011 to 2025). "However, another study showed significant association between MGMT methylation and improved overall survival in diffuse large B-cell lymphoma." (PMID 22132162, 2011).
ependymoma (8 papers, 2006 to 2025). A WHO grade II, slow growing tumor of children and young adults, usually located intraventricularly. "Compared with astrocytic tumors, primary ependymomas also showed lower methylation at MGMT promoter." (PMID 29416789, 2018). "The rationale for the dose-dense TMZ schedule was to target the unmethylated MGMT promoter in ependymomas, since dose-dense TMZ may decrease the level of MGMT." (PMID 34885237, 2021). "As some recurrent anaplastic ependymomas express elevated levels of O6-methylguanine-DNA-methyltransferase, TMZ works against these ependymomas by depleting O-6-methylguanine-DNA methyltransferase." (PMID 34203272, 2021). "The modest activity of TMZ against ependymoma cells has been suggested to be due to the lack of O6-methylguanine-DNA-methyltransferase (MGMT) promoter methylation; however, even when present, MGMT promoter methylation does not correlate with response to TMZ." (PMID 35384591, 2022). "Furthermore, O6-Methylguanine-DNA-methyltransferase (MGMT) upregulation and reduced promoter methylation have also been reported in recurrent ependymomas." (PMID 29416789, 2018). "The tumors suppressor genes RASSF1, CDKN2A, CDKN2B, p14ARF and TP73, as well as other genes potentially involved in the tumorigenesis of ependymomas, such as CASP1, MGMT, TIMP3 and THBS1 are epigenetically silenced by aberrant promoter methylation in subsets of ependymomas." (PMID 19333441, 2009).
oral cancer (8 papers, 2004 to 2025). "MGMT promoter hypermethylation has also been associated with poorer outcomes for oral cancer, including a greater likelihood of nodal metastases, tumor recurrence, and decreased survival." (PMID 22645611, 2012). "Similarly, there was a significant inverse association between MGMT methylation and survival among a sample of American oral cancer patients, while the frequency of MGMT hyper methylation was noticeably lower than that among Iranian patients." (PMID 33883026, 2021). "Fewer studies have considered the methylation of the MLH1 gene in oral cancer compared with the MGMT." (PMID 35888599, 2022). "Tissue breakdown in periodontal disease can be detected through elevated salivary levels of matrix metalloproteinase-8 (MMP-8), while epigenetic alterations, such as hypermethylation in tumor suppressor genes like p16INK4a and MGMT, provide early warning signals for oral cancer." (PMID 41303669, 2025).
rectal cancer (8 papers, 2017 to 2024). A primary or metastatic malignant neoplasm that affects the rectum. "In line with this evidence, MGMT hypermethylation of cell-free DNA from serum was associated with improved response to treatment and higher regression in rectal cancer patients who received 5-FU-based neoadjuvant chemoradiation." (PMID 31390840, 2019). "In addition, MGMT methylation levels in the blood were similar to those in rectal cancer tissues." (PMID 31199091, 2019). "Interestingly, for rectal cancer, SEPT9 methylation levels were significantly higher in stage IV than in stages I, II or III (P = 0.001), whereas both MGMT and SEPT9 methylation levels were significantly lower in patients that underwent neoadjuvant treatment (P = 0.012 and P = 0.002, respectively)." (PMID 29486770, 2018).
small cell lung carcinoma (8 papers, 1997 to 2024). Small cell lung cancer (SCLC) is a highly aggressive malignant neoplasm, accounting for 10-15% of lung cancer cases, characterized byrapid growth, and early metastasis. "A meta-analysis of the role of MGMT promoter methylation in small cell lung cancer showed a correlation with the clinical stage of this cancer type, but not with factors like sex, age, and smoking." (PMID 33546098, 2021). "Collectively, our findings show that Trps1 directly binds to the MGMT gene promoter and induces MGMT transcription in small cell lung cancer cells." (PMID 29601666, 2018). "MGMT promoter methylation was present in 33% (3/9) patients with typical carcinoid, in 22% (2/9) patients with atypical carcinoid, in 22% (8/37) patients with small cell lung cancer and in 8% (1/12) patient with large cell neuroendocrine carcinoma." (PMID 35677534, 2022).